MMS22L (MMS22 like, DNA repair protein)
Description:
Component of the MMS22L-TONSL complex, a complex that promotes homologous recombination-mediated repair of double-strand breaks (DSBs) at stalled or collapsed replication forks. The MMS22L-TONSL complex is required to maintain genome integrity during DNA replication. It mediates the assembly of RAD51 filaments on single-stranded DNA (ssDNA): the MMS22L-TONSL complex is recruited to DSBs following histone replacement by histone chaperones and eviction of the replication protein A complex (RPA/RP-A) from DSBs. Following recruitment to DSBs, the TONSL-MMS22L complex promotes recruitment of RAD51 filaments and subsequent homologous recombination. Within the complex, MMS22L acts by binding ssDNA.
Synonyms: C6orf167; dJ39B17.2
Tractability: PROTAC: ubiquitination databases record sites on it.
Gene: Protein-coding gene on chromosome 6 (97,142,161 to 97,283,224, reverse strand). Ensembl gene ENSG00000146263.
Subcellular location: Nucleus; Chromosome
Subcellular location (Human Protein Atlas): Nucleoplasm
Gene Ontology:
Molecular function: protein binding; single-stranded DNA binding
Biological process: double-strand break repair via homologous recombination; protein localization to chromatin; replication fork processing
Cellular component: chromosome; FACT complex; MCM complex; nuclear replication fork; nucleoplasm; nucleus; site of DNA damage; site of double-strand break
Genetic constraint (gnomAD): Loss-of-function variants: 49 observed, 122.85 expected, observed/expected ratio (o/e) 0.4, 90% interval 0.32 to 0.51. The upper end of that interval is the gene's LOEUF score, 0.51, which puts it in group 2 of 6, group 1 being the genes least tolerant of losing a copy. Missense variants: 1,106 observed, 1,228.6 expected, observed/expected ratio (o/e) 0.9, 90% interval 0.86 to 0.95. Synonymous variants: 445 observed, 445.76 expected, observed/expected ratio (o/e) 1, 90% interval 0.92 to 1.08.
Homologues: Orthologues: chimpanzee MMS22L (98% identical), macaque MMS22L (97% identical), dog MMS22L (87% identical), rabbit MMS22L (87% identical), pig MMS22L (86% identical), guinea pig MMS22L (83% identical), mouse Mms22l (81% identical), rat Mms22l (80% identical), tropical clawed frog mms22l (55% identical), zebrafish mms22l (47% identical), Drosophila melanogaster CG14803 (18% identical).
Diseases named in the same sentence as MMS22L in open-access papers:
MMS22L is named in the same sentence as 26 diseases in open-access papers, as found by Europe PMC text mining. Sharing a sentence is not in itself a finding about the gene and the disease. The quoted sentences say what the papers report.
breast carcinoma (4 papers, 2017 to 2023). "Previous studies have speculated that MMS22L mutations caused genomic instability and promoted certain types of ovarian and breast cancer; however, our data suggested that patients with MMS22L mutations had a better prognosis than patients with wild-type MMS22L in UCEC." (PMID 36276962, 2022). "Additionally, downregulation of MMS22L is associated the bone metastasis in breast cancer." (PMID 34660277, 2021).
esophageal cancer (4 papers, 2017 to 2023). A primary or metastatic malignant neoplasm involving the esophagus. "Genes, such as BOP1, KIF11, and MMS22L, are associated with the progression of various cancers, such as colorectal cancer, gastric cancer, lung, and esophageal cancer, but these genes may be linked with the development of BRCA." (PMID 31311202, 2019). "MMS22L was found to be over-expressed in clinical and esophageal cancers, playing a role in growth and survival of cancer cells." (PMID 37264412, 2023). "MMS22L has been described as an oncogene in lung and esophageal cancer." (PMID 28423700, 2017).
colorectal cancer (3 papers, 2019 to 2025). A primary or metastatic malignant neoplasm that affects the colon or rectum. "Additionally, the activation of the SOX9/MMS22L-dependent DNA damage pathway promotes oxaliplatin resistance in colorectal cancer." (PMID 40240356, 2025).
esophageal squamous cell carcinoma (1 paper, 2022). Esophageal squamous cell carcinoma (ESCC) is a type of esophageal carcinoma (EC) that can affect any part of the esophagus, but is usually located in the upper or middle third. "Conversely, a lower expression of MMS22L was associated with worse clinical outcomes in esophageal squamous cell carcinoma, suggesting MMS22L is a tumor suppressor." (PMID 36276962, 2022).
glioblastoma (1 paper, 2023). The most malignant astrocytic tumor (WHO grade IV). "We also confirmed that CSCs in glioblastomas required MMS22L." (PMID 37298484, 2023).
hepatocellular carcinoma (1 paper, 2022). A malignant tumor that arises from hepatocytes. "Further, by combining multi-cohorts and molecular biology experiments, this study identifies the vital role and clinical significance of MMS22L in hepatocellular carcinoma (HCC)." (PMID 36276962, 2022). "Eventually, we investigated the role of MMS22L in hepatocellular carcinoma (HCC)." (PMID 36276962, 2022).
lung adenocarcinoma (1 paper, 2023). A carcinoma that arises from the lung and is characterized by the presence of malignant glandular epithelial cells. "MMS22L gene amplification was very rare in all cancers assessed, and point mutations were the most common variations in stomach and lung adenocarcinomas." (PMID 37298484, 2023).
lung carcinoma (1 paper, 2023). "Moreover, given its association with Pou3f2 and Mms22l, Pelomonas might play a role in susceptibility to lung cancer and other related lung diseases." (PMID 37264412, 2023).
Lymph node metastasis (1 paper, 2021). "Lymph node metastasis was significantly associated with low MMS22L expression (p < 0.01)." (PMID 34660277, 2021). "In the present study, we found that low MMS22L expression, immunohistochemically stained and analysed semiquantitatively in ESCC samples, was a useful predictor of worse responses to NCRT and lymph node metastasis, and enhanced migration and resistance to 5-FU in the TE-1 cell line." (PMID 34660277, 2021).
melanoma (1 paper, 2017). A malignant, usually aggressive tumor composed of atypical, neoplastic melanocytes. "Although HERPUD1, INSIG1 and MMS22L were mutated in more than one of the melanoma cell lines, only Ma-Mel-86a cells were recognized by the respective T cell clones." (PMID 28423700, 2017).
oesophageal cancer (1 paper, 2021). "In contrast to our findings, a previous study found that MMS22L expression was upregulated in lung and oesophageal cancer tissues compared with that in adjacent normal lung and oesophageal tissues, and MMS22L was identified as an oncogene." (PMID 34660277, 2021).
paraganglioma (1 paper, 2022). A benign or malignant neoplasm arising from paraganglia located along the sympathetic or parasympathetic nerves. "After integrating TMB data and MMS22L expression in pan-cancer, the TMB of 11 types of tumors (LUAD, COAD, READ, STES, KIPAN, STAD, prostate adenocarcinoma (PRAD), pheochromocytoma and paraganglioma (PCPG), ACC, and KICH) were positively related to MMS22L expression." (PMID 36276962, 2022).
prostate carcinoma (1 paper, 2023). A carcinoma that arises from epithelial cells of the prostate gland. "Here, using a genome-wide CRISPR-Cas9 knockout screen, the authors identify MMS22L as a biomarker for sensitivity to PARP inhibition in BRCA1/2-proficient prostate cancer." (PMID 36650183, 2023).
cancer (11 papers, 2017 to 2026). A tumor composed of atypical neoplastic, often pleomorphic cells that invade other tissues. "In addition, we are the first to analyze the association of MMS22L with the immune system in pan-cancer and its role in immunotherapy." (PMID 36276962, 2022). "Our results indicated that MMS22L is associated with diverse cancers and may affect the effectiveness of therapy by associating with immune cells." (PMID 36276962, 2022). "We characterized the hallmark of MMS22L and preliminarily explored the potential mechanism of action of MMS22L and its association with the prognosis of tumor patients, immune cell infiltration, and genomic heterogeneity in pan-cancer." (PMID 36276962, 2022). "In addition, the correlation of MMS22L mRNA expression levels with tumor mutational burden, microsatellite instability, homologous recombination deficiency, and loss of heterozygosity in pan-cancer was also described in this study." (PMID 36276962, 2022). "In order to confirm the relationship between MMS22L expression and cancer immunity, we examined the correlation between MMS22L expression and the infiltration of immune cells in pan-cancer using the TIMER2 database." (PMID 36276962, 2022). "MMS22L is widely expressed in human tumor tissues and plays different roles in the occurrence and development of various cancers, thus highlighting the possibility of MMS22L as a potential target for cancer therapy." (PMID 36276962, 2022). "Here, we reported the landscape of MMS22L using multi-omics data and identified the relationship between the MMS22L status and pan-cancer prognosis." (PMID 36276962, 2022). "Although this study characterizes the role of MMS22L in pan-cancer and reveals an important role of MMS22L in HCC, there are inevitably some limitations in this study." (PMID 36276962, 2022). "To gain a basic understanding of MMS22L in pan-cancer, we used the TCGA and GTEx databases to evaluate the expression level of MMS22L in cancer compared with that in normal tissues." (PMID 36276962, 2022). "Overall, this study is the first to reveal the landscape of MMS22L in pan-cancer and preliminarily explores the potential role of MMS22L in HCC." (PMID 36276962, 2022). "Collectively, our findings reveal the essential role of MMS22L as a tumor-regulating gene in human cancers while further emphasizing its feasibility as a novel molecular marker in HCC." (PMID 36276962, 2022). "Next, since the prognosis of tumor patients remains the most concerning issue in cancer research, some studies have characterized the critical role of MMS22L in tumors and its relationship with prognosis." (PMID 36276962, 2022). "We hope this pan-cancer analysis of MMS22L will help guide basic, translational, and clinical research targeting MMS22L in human cancers." (PMID 36276962, 2022). "Although MMS22L is an attractive target for cancer therapy, its application in tumor therapy still faces numerous problems." (PMID 36276962, 2022). "Based on these observations, both Pou3f2 and Mms22l might serve as cancer therapy targets, which could be aided by the mechanistic understanding of a possible interaction with Pelomonas." (PMID 37264412, 2023). "Furthermore, this study was the first to characterize the relationship between mRNA expression of MMS22L and immune cell infiltration in the tumor microenvironment in human cancer." (PMID 36276962, 2022). "Therefore, we believe that the role of tumor vaccine after introducing other cancer-testis antigens is likely to be the fundamental role of MMS22L in tumor immunotherapy." (PMID 36276962, 2022). "Therefore, a comprehensive understanding of the molecular characterization and clinical relevance of MMS22L in human cancer is urgent." (PMID 36276962, 2022). "Understanding the aberrant expression and genomic alterations of MMS22L may help to clarify its role in cancer prognosis and treatment." (PMID 36276962, 2022).
cancer (continued). "Therefore, we grouped tumor samples according to MMS22L mRNA expression levels and performed GSEA analysis to explore the role and potential mechanism of MMS22L in pan-cancer." (PMID 36276962, 2022). "Additionally, DDX27, MDM2, RNF40, MMS22L, CCNK and LRP1B were detected as missense mutational cancer gene." (PMID 34313788, 2021). "However, the role of MMS22L in human cancers remains unclear." (PMID 36276962, 2022). "To elucidate the potential mechanism of action of MMS22L, we further analyzed the pathways involved in MMS22L using the GSEA function in pan-cancer." (PMID 36276962, 2022). "Nevertheless, not all reports suggested that MMS22L functioned as a cancer-promoting factor, promoting the occurrence and development of cancer." (PMID 36276962, 2022). "The interaction between MMS22L and NFKBIL2 has been proposed as another mechanism for participating in the NFKB pathway in cancer cells, further identifying it as a promising target for cancer therapy." (PMID 36276962, 2022). "On the other hand, DDX27, RNF40, MMS22L and CCNK have not been reported as mutational cancer genes in previous studies." (PMID 34313788, 2021).
tumor (6 papers, 2021 to 2026). "In previous studies, a higher expression of MMS22L in tumor tissues of ESCC was associated with better survival." (PMID 36276962, 2022). "The results of this study demonstrate the status of MMS22L and its association with prognostic data and genomic heterogeneity of tumor patients." (PMID 36276962, 2022). "Recent studies have shown that low expression of MMS22L is associated with poor survival and lymph node metastasis and enhances tumor cell migration in ESCC, suggesting the feasibility of MMS22L as a tumor suppressor gene." (PMID 36276962, 2022). "Furthermore, MMS22L plays a key role in tumor progression and is associated with poor prognosis in patients with HCC, highlighting the therapeutic and diagnostic potential of MMS22L in HCC." (PMID 36276962, 2022). "However, in tumor cells, MMS22L mutations persist throughout tumor development." (PMID 36276962, 2022). "The expression level of MMS22L in tumor tissues was significantly higher than that in adjacent normal tissues in different HCC cohorts." (PMID 36276962, 2022). "MMS22L, for instance, was detected in lung cancers as an oncogene involved in tumor proliferation and metastasis." (PMID 36276962, 2022). "The previous analysis showed that MMS22L had different immunoregulatory functions in different tumor types and correlated with immune cells in the tumor microenvironment." (PMID 36276962, 2022). "Our findings showed that MMS22L had a broad expression pattern in most tumor types and was abnormally expressed in most tumor tissues, indicating the potential of MMS22L as a tumor marker." (PMID 36276962, 2022). "MMS22L protein expression was significantly reduced in seven tumour tissues compared with that in normal adjacent tissues." (PMID 34660277, 2021). "In conclusion, low expression of MMS22L is associated with poor response to NCRT, worse survival, lymph node metastasis, and enhanced migration of tumour cells in ESCC." (PMID 34660277, 2021). "Altogether, these results suggest that the roles of MMS22L in different tumors are diverse and complex and suggest that MMS22L may be a promising target for tumor therapy." (PMID 36276962, 2022). "The previous analytical results suggested that MMS22L played an essential role in tumor progression and prognosis; however, its mechanism of action remains unclear." (PMID 36276962, 2022). "On the other hand, these results suggest a possible link between MMS22L and tumor immunotherapy." (PMID 36276962, 2022). "Furthermore, MMS22L was downregulated at both the mRNA (p < 0.001) and protein levels in tumour tissues compared with that in normal tissues." (PMID 34660277, 2021). "Previous studies have shown that MMS22L plays critical roles in the DNA damage response and repair, affecting the response of tumour cells to DNA-damaging agents, such as camptothecin (CPT), ionising radiation (IR), hydroxyurea (HU), and methyl methanesulfonate (MMS)." (PMID 34660277, 2021). "Moreover, the xenograft assay results showed that oxaliplatin abrogated tumor growth from cells with MMS22L downregulation in mice." (PMID 34124145, 2021). "However, tumor heterogeneity limits our knowledge about the role of MMS22L in human tumors." (PMID 36276962, 2022). "Therefore, in this study, we first explored the correlation between the expression level of MMS22L and immune cell infiltration in the human tumor microenvironment and further compared the role of MMS22L in different immunotherapy cohorts through existing clinical studies." (PMID 36276962, 2022). "Targeting MMS22L may contribute to the development of tumor vaccines." (PMID 36276962, 2022). "In conclusion, miR-8485-mediated downregulation of UBN2, ETS1, MMS22L, GSK3B, and SLC44A1 inhibits tumor progression through mechanisms involving cell cycle arrest, metastasis inhibition, apoptosis induction, and choline metabolism." (PMID 40095604, 2025).
tumor (continued). "Previous reports mainly identified MMS22L as a potential oncogene, which enhanced its nuclear localization and stability by binding to NFKBIL2 to promote tumor cell growth." (PMID 36276962, 2022). "Images captured with immunofluorescence showed that MMS22L protein was predominantly localized and distributed in the nucleus of HEK293, U-251 MG, and U-2 OS tumor cell lines." (PMID 36276962, 2022).
MMS22L also shares sentences with these, for which no sentence is quoted: anemia (1 paper); colon cancer (1); Fanconi anemia (1); gastric cancer (1); lung diseases (1); non-small cell lung carcinoma (1); panic disorder (1); pheochromocytoma (1); prostate adenocarcinoma (1); sarcopenia (1); small cell lung carcinoma (1).